EGFR (epidermal growth factor receptor)
Diseases named in the same sentence as EGFR in open-access papers (continued):
Sharing a sentence is not in itself a finding about the gene and the disease.
tumor (continued). "In vivo drug response of xenotransplanted RAS mutant CRC organoids confirmed the arrest in tumor growth upon dual inhibition of the EGFR-MEK-ERK pathway." (PMID 27845624, 2016). "In this study, we describe a novel recombinant chimeric protein, dsRBEC, which can bind polyIC and deliver it selectively into EGFR over-expressing tumor cells." (PMID 27598772, 2016). "On the other hand, as a result of erlotinib therapy, changes can occur in the size of the tumor, its concentration of vital tumor cells and possibly its EGFR density." (PMID 26857779, 2016). "The results from our in-vitro model are suggestive of EGFR being a master regulator of cell survival not only in the bulk tumour but also in CTC-forming clusters." (PMID 27643613, 2016). "In fact, the extracellular domain mutations R451C, S464L, G465R, K467T, I491M and S492R of the EGFR (all located in exon 12) were found in post-therapeutic tumor subclones or antibody-resistant cell lines by next-generation or sanger sequencing." (PMID 27119512, 2016). "The tumor tissues of NSCLC patients were all in phase IV, had EGFR mutations, and had high expression of phosphorylated pRb." (PMID 27825114, 2016). "The resistance mechanisms to 3G EGFR-TKIs were discovered either via preclinical investigations, clinical liquid biopsy, or tumor re-biopsy." (PMID 27912760, 2016). "In situ tumor staining showed that EGFR expression was significantly stronger in responders than in non-responders." (PMID 26646697, 2016). "EAI045 in combination with cetuximab also induced marked tumor shrinkage in the mouse model carrying L858R/T790M/C797S, a mutant known to be resistant to all third-generation EGFR TKIs." (PMID 27448564, 2016). "Patients harbouring tumours with an altered EGFR genotype were more frequently CTC-positive compared to patients with EGFR wildtype tumours." (PMID 27302574, 2016). "Groups of three tumor samples studied by IHC were selected from the most RNA-overexpressed samples for EGFR, MET or CDK6, respectively." (PMID 27329726, 2016). "Analysis of tumor tissue lysates by phospho-RTK array showed a prominent tyrosine phosphorylation of EGFR, ERBB4, INSR and IGF1R in control which was remarkably decreased in tumor from treated mice." (PMID 27374103, 2016). "In the multivariate analysis for CSS, EGFR gene amplification was analysed together with tumour stage, histological differentiation grade and patient age at the time of diagnosis." (PMID 27387915, 2016). "This represents one tenth of the tumour to blood ratio and half of the tumour to tissue ratio obtained with the anti-EGFR nanobody 99mTc-D10." (PMID 26912069, 2016). "Tumor rebiopsy shall become a norm before commencement of 2nd EGFR-TKI therapy after failure to the first one especially when patients were advised to join the clinical trials using T790M-specific TKI." (PMID 26911310, 2016). "Previous studies in our laboratory uncovered a novel link between HNSCC tumor response to the EGFR TKI erlotinib and interleukin-1 (IL-1)-mediated inflammation." (PMID 27738319, 2016). "Additional studies demonstrated enhanced binding to cancers with EGFR amplification compared to commercial anti-EGFR antibodies and minimal binding to non-tumor tissues in a murine distribution bioassay." (PMID 27153091, 2016). "In our current study, we chose to target EGFR on BCBMs because EGFR plays an important role in tumor cell proliferation, motility, and survival." (PMID 27050072, 2016). "Second, PI-sEGFR derives from a proteolytic cleavage of the EGFR trans-membrane form, which is expressed in tumor cell lines with high EGFR expression." (PMID 27104520, 2016).
tumor (continued). "Our findings demonstrated that hypoxia/reoxygenation and TGF-β were crucial factors in Nrf2-mediated tumor resistance, which was correlated with EGFR activation." (PMID 26904167, 2016). "Several immune effector cells in the body have the ability to recognize target molecules on the tumor cell surface, like EGFR on CRC cells, through their FcR-mediated binding of antibodies directed against these targets, leading to potent antitumor immunity." (PMID 27314237, 2016). "These new drugs have lower affinity for the ubiquitous wt EGFR compared to the tumour-specific mutant EGFR and therefore exhibit a more favourable toxicity profile." (PMID 27350784, 2016). "Analysis of tumor from the 2015 (post-trial) recurrence showed that EGFR and IGF-1R were still detectable, but with reduced intensity compared with the 2008 recurrence, and reduced nuclear IGF-1R." (PMID 27200287, 2016). "EGFR is overexpressed in over 90 % of HNSCC but with a huge discordance between the primary tumor and CTC." (PMID 27465596, 2016). "Patients with epidermal growth factor receptor (EGFR) or anaplastic lymphoma kinase (ALK) genomic tumor aberrations should have disease progression on FDA-approved therapy for these aberrations prior to receiving pembrolizumab." (PMID 29152394, 2016). "Although extracellular galectin-3 per se has no influence in cellular apoptosis, it's binding to cell surface receptors such as EGFR can sensitize tumor cells to chemotherapeutics." (PMID 27835877, 2016). "The kinase activity of EGFR is often dysregulated in tumor cells, and its aberrant activation can lead to enhanced cell survival, proliferation, invasion, and metastasis." (PMID 27612423, 2016). "Here, we show that through shRNA knockdown studies, TGFβ2 directly mediates the survival of the adaptive EGFR-TKI drug-escaping tumor cells, and that it also directly regulates the mitochondrial BCL-2/BCL-xL expression downstream, but not BIM." (PMID 27852038, 2016). "As a result of “oncogene-addiction”, EGFR TKIs often yields tumor response that can be rapid and remarkable." (PMID 27852038, 2016). "MCF10A cells are highly dependent on EGFR pathway, thus it represents a useful tool to study EGFR signalling, avoiding perturbations derived from tumor transformation." (PMID 27708224, 2016). "The expression of GLI1, Shh and NF-κB correlated with clinico-pathological variables including histological type, tumor grade, tumor size, lymph node metastasis, and EGFR, ErbB2, estrogen receptor (ER) and progesterone receptor (PR) expression." (PMID 26843616, 2016). "The finding of a potential interaction between the expression of EGFR and response to adjuvant chemotherapy in PB-type tumours needs validation, and merits further study." (PMID 27070783, 2016). "Lately, Steinway found that the EGFR pathway acts as a compensatory survival mechanism upon c-Met inhibition in human c-Met-positive HCC, and combined inhibition of both c-Met and EGFR oncogenic pathways provides superior suppression of HCC tumor growth." (PMID 27669229, 2016). "In our study, we evaluated three widely used serum tumor markers in NSCLC and their cytologic counterparts to evaluate for EGFR mutation prediction." (PMID 26979333, 2016). "In contrast, all seven EGFR-mutated tumours had lower ZEB1 and the levels of ZEB1 were significantly lower in EGFR mutant tumours than that in EGFR wild-type tumours (Student's t-test P=0.027) or in KRAS mutant tumours (Student's t-test P=0.013)." (PMID 27456471, 2016). "Further, we and others have shown that miR-7-5p is capable of sensitizing other resistant tumor types to targeted therapies, such as the EGFR tyrosine kinase inhibitor erlotinib." (PMID 27203220, 2016).
tumor (continued). "In the multivariate model for TTR, EGFR gene amplification was analysed together with tumour stage, histological differentiation grade and tumour location." (PMID 27387915, 2016). "Selumetinib (MEKi) as a monotherapy showed little efficacy in both P8T and P26T, but combination therapy confirmed previous findings that MEKi sensitizes RAS mutant tumor cells to EGFR/HER2 inhibition." (PMID 27845624, 2016). "Classic studies of EGFR-mutant clinical resistance to precision therapy were based on tumor rebiopsies late during clinical tumor progression on therapy." (PMID 27852038, 2016). "High membranous or membranous + cytoplasmic EGFR IHC staining intensity (2+/3+) was observed in 72 (32.7 %) of the tumours, while 2+/3+ HER2 IHC staining intensity was present in 31 (14.1 %) tumours." (PMID 27387915, 2016). "At multivariate analysis, ECOG-PS, tumor stage, histology, EGFR status and NLR were predictors of OS." (PMID 27029035, 2016). "As with the first- and second-generation EGFR TKIs, tumor evolution leads to resistance to third-generation TKI’s." (PMID 27200298, 2016). "We also analyzed tumor samples for EGFR protein level and ERK1/2 and Akt activation and found a drastic reduction in the SHP2-silenced tumors." (PMID 26728598, 2016). "In this review, we discuss available evidence on this topic, focusing on the different EGFR molecular alterations in tumor tissue, in relation with different treatments and settings." (PMID 27556186, 2016). "Considering the role of EGFR in tumor progression, targeting it for NSCLC treatment is an effective approach." (PMID 27653775, 2016). "Overall, a rechallenge with anti-EGFR agents was observed in 52 patients with presumably KRAS wild-type tumours." (PMID 27389564, 2016). "In many cancer types, EGFR is the driven force that makes these tumor cells grow faster than normal." (PMID 27223425, 2016). "Other cell surface receptors studied in this experiment included EGFR and VEGFR, which were receptor tyrosine kinases (RTKs) associated with tumor progression." (PMID 27589842, 2016). "In our previous study, we used a high-resolution melt (HRM) curve to screen EGFR statuses in AC primary and metastasized tumours and found different EGFR statuses among these tumours." (PMID 27046167, 2016). "In details, it has been demonstrated that tumor cells treated with cisplatin show increased EGFR activation which can be considered a survival response to the treatment." (PMID 27884140, 2016). "FED6 showed high uptake in EGFR overexpressing tumours compared to low EGFR expressing tumours and was metabolically stable." (PMID 27552105, 2016). "Targeting EGFR with Pan‐IR700 has robust potential to provide a tumor‐specific mechanism for eliminating residual disease in the surgical setting, thereby increasing therapeutic efficacy, prolonging progression‐free survival, and decreasing morbidity." (PMID 27167827, 2016). "An ARMS amplification revealed that the EGFR status of the metastasized cells was consistent with the corresponding primary tumour components." (PMID 27046167, 2016). "The successful tumour visualization with high uptakes of the anti-EGFR nanobody 99mTc-D10 can be explained by the small size of the nanobody enabling a good tissue penetration." (PMID 26912069, 2016). "Tumor heterogeneity has been commonly recognized as another reason for discrepant response to EGFR-TKI treatment among EGFR-mutant patients." (PMID 27418143, 2016). "The concordance for T790M detection by digital PCR between tumor tissue and plasma DNA obtained after the development of resistance to EGFR-TKI therapy was previously found to be 64%." (PMID 27542267, 2016). "Our study shows that 99mTc-D10 represents a versatile tool for the specific detection of small EGFR overexpressing tumour lesions and the assessment of EGFR expression in tumours by in vivo SPECT." (PMID 26912069, 2016).
tumor (continued). "Among the third-generation EGFR TKIs, osimertinib was the only inhibitor demonstrating sustained tumor regression in both preclinical and clinical models." (PMID 28149837, 2016). "Our data suggest that the PIK3/AKT/mTOR pathway is more active in left- than right-sided CRC, which provides a possible explanation for the fact that efficacy of anti-EGFR therapy differs by location of primary tumor." (PMID 27296289, 2016). "Asporin promoted the migration and invasion of the tumor cells partially through an EGFR/Src/cortactin- signaling pathway." (PMID 27705916, 2016). "The patient was in good health for four years until lung CT revealed tumor nodules in left lung in 2013 and the patient began taking icotinib, an EGFR inhibitor approved for clinical usage by China Food and Drug Administration (CFDA)." (PMID 26654941, 2016). "Conversely, high post-treated soluble EGFR extracellular domain levels correlated with tumor size reduction on post-treatment metabolic SUV response assessment (bias adjusted Spearman's rho = −0.49, z-test p = 0.03; β = −0.42 se = 0.23, F test p = 0.08)." (PMID 27028852, 2016). "This favorable toxicity profile can be explained by a kinetic binding model of anti-EGFR antibodies, where intermediate affinity of nimotuzumab (KD = 10−9M) to the receptor, results in a high tumor uptake and low uptake into normal tissues." (PMID 27050148, 2016). "Collectively, EGFR knockdown exhibited a similar phenotype as miR‐134 overexpression, and rescue experiments confirmed that the tumour suppressive function of miR‐134 is mediated partly by down‐regulating EGFR." (PMID 27241841, 2016). "The therapeutic effect of existing EGFR-targeted therapies is achieved by blocking EGFR signalling in the tumour." (PMID 26956916, 2016). "Plasma specimens from all subjects as well as tumor tissue or malignant pleural effusion or ascites fluid from 41 patients were collected after the development of EGFR-TKI resistance." (PMID 27542267, 2016). "EGFR is overexpressed and/or activated in many human tumors including SCCs and is often correlated to tumor aggressiveness." (PMID 26918609, 2016). "Twenty-two patients with ADC subtype and EGFR sensitive mutations received TKI treatment with a median PFS of 16 months and all the patients were observed with tumor regression after 3-months treatment." (PMID 26789109, 2016). "Our results suggest that the activity of the EGFR signaling pathway, in addition to the specific genetic alteration, is an important determinant of tumor aggressiveness." (PMID 27738329, 2016). "Western blot analysis performed on tumor samples indicated that the EGFR level remained higher at the time when tumors were harvested." (PMID 26820293, 2016). "124I-Cetuximab uptake measurements demonstrated that AT13387 significantly reduced EGFR expression in tumours with high expression and tumours with low expression by 67 % (p < 0.001) and 40 % (p < 0.05), respectively." (PMID 26627081, 2016). "In summary, these combined data would suggest that a part of tumor cells have activated HH pathways to survive against EGFR-TKI treatment, and then shifted their oncogenic addiction to HH pathway for a long-term maintenance of cell growth." (PMID 27015549, 2016). "Gene copy numbers were analysed with EGFR or HER2 SISH in all tumours with high EGFR or HER2 IHC staining intensity." (PMID 27387915, 2016). "To investigate the role for EGFRvIII activation in tumor phenotype we used a neural progenitor cell-based murine model of GBM driven by EGFR signaling and generated tumor progenitor cells with high and low EGFRvIII activation, pEGFRHi and pEGFRLo." (PMID 27738329, 2016). "The altered RTKs in UC have been reported and associated with tumor cell proliferation and survival, including FGFR3 activation, EGFR amplification, ERBB3 mutation, and ERBB2 mutation or amplification." (PMID 27793038, 2016).
tumor (continued). "Erlotinib-resistant (ER) tumours arising in these mice reproducibly acquired EGFR T790M in vivo, while rociletinib monotherapy prevented the emergence of T790M clones and maintained tumour stasis for ∼100 days." (PMID 27283993, 2016). "We have found miR-7 to inhibit EGFR expression and signaling in A549 cells, consistent with it having a tumour suppressive effect." (PMID 26308064, 2015). "Heterodimerization is consistent with the increased expression of phosphorylated HER2 and EGFR observed when tumor concentrations of lapatinib increased in the 2–10 μM range." (PMID 26571496, 2015). "EGFR is a critical regulator of cellular proliferation and differentiation and plays a central role in tumor proliferation and growth." (PMID 26317547, 2015). "During the course of treatment, it is difficult to repeatedly acquire appropriate tumor samples for monitoring responses to EGFR-TKI." (PMID 25888731, 2015). "Results showed that EGFR inhibition with cetuximab can reduce tumor growth and angiogenesis in HNSCC." (PMID 25723392, 2015). "Mitogen-inducible gene-6 (MIG-6) is a potent inhibitor of the EGFR and has been demonstrated to function as a tumor suppressor." (PMID 26065894, 2015). "This can enable the tumor cell to overcome the effect of EGFR-targeted drugs that aim to disrupt kinase activity of the membrane-bound receptor." (PMID 25885672, 2015). "Mice that received either EGFR-CAR- or mock-transduced NK-92 cells had significantly reduced tumor growth as determined by bioluminescence imaging, compared to those injected with Hank’s buffered salt solution (HBSS)." (PMID 26155832, 2015). "The importance of representative model systems of EGFR-amplified GBM for research is highlighted by recent reports which described the occurrence of circulating tumor cells (CTCs) in the blood of more than 20% of GBM patients." (PMID 26136784, 2015). "In every tumor that exhibited EGFR, PDGFRA, NTRK1, MDM2, MDM4, or CDK4 amplification, the increased copy number was contained within, or contained translocations into, a suspect chromothriptic region." (PMID 26328271, 2015). "In this study, we describe the anti-tumor effect of TAE226 on EGFR-mutant cells in vitro and in vivo and investigated the anti-tumor mechanism of TAE226 in EGFR-mutant cells." (PMID 26090892, 2015). "In summary, we provide evidence that intermittent high-dose treatment of EGFR-mutant tumors with erlotinib enables enhanced tumor shrinkage and prolonged PFS, while limiting toxicity in a mouse xenograft study." (PMID 26540572, 2015). "A recent clinical trial described a partial response to the EGFR/HER2 inhibitor BIBW2922 in a HER2 mutant tumor, suggesting that this new drug is a promising treatment strategy." (PMID 25760072, 2015). "The SUVmax was significantly different according to the tumor grade, ER, EGFR, and Ki-67 in IDCs, but only for Ki-67 in ILCs." (PMID 25889560, 2015). "Epidermal growth factor receptor (EGFR) is a critical mediator of tumor cell survival and proliferation." (PMID 25915533, 2015). "Based on in vitro studies and xenograft models, STAT3 is considered to play a tumour-promoting role in EGFR mutant NSCLC13, 14, 16, 18, therefore, inhibition of STAT3 is considered as therapeutic intervention in lung ACs46." (PMID 25734337, 2015). "In this study, all EGFR amplified cases demonstrated a pattern of clusters of tumor cells with high level amplification." (PMID 26369702, 2015). "Epidermal growth factor receptor (EGFR) is an important mediator of tumor cell survival and proliferation." (PMID 25915533, 2015).